XIAP (X-linked inhibitor of apoptosis)
Diseases named in the same sentence as XIAP in open-access papers (continued):
Sharing a sentence is not in itself a finding about the gene and the disease.
chronic lymphocytic leukemia (11 papers, 2008 to 2022). "These include cell cycle regulatory genes such as fos, cyclin D, c-Myc, pim1 and anti-apoptotic genes such as B-cell CLL/Lymphoma-2 (Bcl-2), Bcl-xL, survivin and X-linked inhibitor of apoptosis protein (XIAP)." (PMID 31731457, 2019). "TP-0903 reduces anti-apoptotic proteins like BCL-2, MCL-1, and XIAP, and enhances dose-dependent chronic lymphocytic leukemia (CLL) cell death." (PMID 35311091, 2022). "An additional antiapoptotic protein, XIAP was found to be sensitive to CDK inhibition in Chronic Lymphocytic Leukemia (CLL)." (PMID 22558078, 2012). "As XIAP inhibition sensitised chronic lymphocytic leukaemia cells and RCC cells to Fas-induced apoptosis, we treated the parental cells, mock transfectants, and clone nos." (PMID 18283311, 2008). "CDK9 is also responsible for transcription of anti-apoptotic factors, that belong to Bcl-2 superfamily: Mcl-1 (Myeloid cell leukaemia-1), Bcl-2 (B-cell CLL/Lymphoma 2), and XIAP (X-linked inhibitor of apoptosis), making CDK9 potential source of inhibition for anti-tumor purposes." (PMID 33805800, 2021). "Moreover, curcumin exhibited apoptosis in B-cell chronic lymphocytic leukemia (CLL-B) via downregulation of STAT3, AKT, NF-κB, and X-linked inhibitor of apoptosis protein (XIAP)." (PMID 31590362, 2019). "Thus it has been shown that both UCN-01 and flavopiridol decrease the expression of Mcl-1, XIAP, BAG-1, and Bcl-2 in B-cell chronic lymphocytic leukemia cells." (PMID 23527225, 2013).
liver cancer (11 papers, 2016 to 2026). An epithelial or non-epithelial malignant neoplasm that arises from the liver. "In conclusion, increased XIAP expression is associated with the progression of liver cancer after MWA treatment." (PMID 39917292, 2025). "TNF-related apoptosis-inducing ligand (TRAIL)-induced apoptosis of liver cancer cells is associated with the degradation of cIAP-1 and X-linked IAP (XIAP)." (PMID 34800438, 2021). "NQO1 potentiates the apoptosis evasion of liver cancer cell through upregulating X-linked inhibitor of apoptosis protein (XIAP) protein stability." (PMID 31842909, 2019). "Furthermore, Kaplan–Meier survival analysis revealed that high XIAP expression or low miR-192s levels are associated with poorer overall survival and recurrence-free survival rates of liver cancer patients." (PMID 35847962, 2022). "Moreover, we found that silencing circKIF5B markedly reduced the proliferation, invasion, and metastasis of liver cancer cells by sponging the miR-192 family, thus decreasing the expression of X-linked inhibitor of apoptosis (XIAP)." (PMID 35847962, 2022). "Furthermore, we found that inhibiting circKIF5B expression significantly reduced the invasion, metastasis, and proliferation of liver cancer cells via sponging of the miR-192 family, which downregulated the expression of X-linked inhibitor of apoptosis (XIAP)." (PMID 35847962, 2022). "We detected the expression of XIAP protein after ablation in primary liver cancer patients using immunohistochemistry." (PMID 39917292, 2025). "A few studies indicate that inhibition of XIAP can be used for anti-cancer therapy for liver cancer." (PMID 39917292, 2025). "The XIAP inhibitor AZD5582 mitigates the progression of liver cancer via inducing cell apoptosis and inhibiting cell proliferation in vitro and in vivo." (PMID 39917292, 2025). "This indicates that XIAP plays a significant role in the progression of liver cancer after MWA treatment." (PMID 39917292, 2025). "The quantified results of images indicated that the protein expression of XIAP was increased in the recurrent liver cancer tissue of patients who previously received MWA treatment." (PMID 39917292, 2025). "The effect was to down-regulate the expression of its target gene XIAP, thereby activating caspase-3, inducing apoptosis of liver cancer cells." (PMID 35096574, 2021). "MiR-23a then down-regulates the expression of its target gene XIAP, thereby activating the activity of caspase-3 and inducing apoptosis of liver cancer cells." (PMID 35096574, 2021). "Knockdown XIAP in HepG2 was able to significantly reduce resistant effect in liver cancer cells by decreasing the resistant fold to 0.254 with JNJ treatment." (PMID 29581832, 2018). "To study universality and importance of c-Fos/AP-1/XIAP signaling pathway in therapeutic resistance, we tested our finding in another cancer such as liver cancer HepG2 cells." (PMID 29581832, 2018). "Our study identified a new regulatory pathway, c-Fos/AP-1/XIAP, that contributes the induction of drug resistant in breast and liver cancer cells." (PMID 29581832, 2018). "The activation of c-Fos/AP-1/XIAP signaling pathway is confirmed in other cancer type such as liver cancer." (PMID 29581832, 2018). "For example, UA induces apoptosis via down-regulation of XIAP and mitochondrial-dependent pathway in human liver cancer HepG2, Hep3B, Huh7 and HA22T cell lines." (PMID 27104510, 2016). "The expression levels of XIAP and XIAP-associated factor-1(XIF1) also positively correlated with survival in primary liver cancer patients." (PMID 27057629, 2016). "Altogether, the results demonstrated that the XIAP inhibitor AZD5582 in combination with IMWA drastically inhibited the progression of liver cancer tissue in immunity-intact mice, and the XIAP inhibitor also inhibited the progression of liver cancer tissue in immunity-deficient mice." (PMID 39917292, 2025). "We find a significant increased expression of XIAP in the recurrent liver cancer." (PMID 39917292, 2025).
liver cancer (continued). "The XIAP inhibitor AZD5582 and heat treatment synergistically induce apoptosis of liver cancer cells, and inhibit proliferation and migration of liver cancer cells in vitro." (PMID 39917292, 2025). "Notably, recent reports and our previous study showed that primary liver cancer, which usually produces AFP, also expresses high level of XIAP." (PMID 27057629, 2016).
triple-negative breast carcinoma (11 papers, 2016 to 2025). An invasive breast carcinoma which is negative for expression of estrogen receptor (ER), progesterone receptor (PR), and human epidermal growth factor receptor 2 (HER2). "Clinically, XIAP over-expression was significantly associated with tumor size (p = 0.0044), extra-nodal extension (p = 0.0041), poorly differentiated tumor (p < 0.0001), triple negative breast cancer (0.0019) and infiltrative ductal carcinoma subtype (p = 0.002)." (PMID 28893228, 2017). "Previous study reported about the mechanism of IITZ-01 decreases IAP family protein involving cIAP1, XIAP and survivin in triple-negative breast cancer cells." (PMID 32825566, 2020). "miR-200bc/429 cluster modulates multidrug resistance of human cancer cell lines by targeting Bcl-2 and XIAP; microRNA-200c downregulates XIAP expression to suppress proliferation and promote apoptosis of triple-negative breast cancer cells." (PMID 32309578, 2016). "Furthermore, miR-200c targets the X-linked inhibitor of apoptosis protein (XIAP), thereby inhibiting the proliferation of triple-negative breast cancer cells and promoting apoptosis." (PMID 39859424, 2025). "Instead, the downregulation of X-linked inhibitor of apoptosis (XIAP) and survivin, two pro-survival proteins, under Rac inhibition by NCS23766 was shown to promote cell death in triple-negative breast cancer cells regardless of Bcl2 and cyclin D1 expression." (PMID 37316799, 2023). "For example, overexpression of CCT2 could promote triple-negative breast cancer cell chemoresistance and cell migration and invasion via the AKT/GSK3β/β-catenin and XIAP/Survivin pathways." (PMID 37006287, 2023).
acute lymphoblastic leukemia (10 papers, 2014 to 2024). Leukemia with an acute onset, characterized by the presence of lymphoblasts in the bone marrow and the peripheral blood. "In acute lymphoblastic leukemia, miR-24-3p induced cell apoptosis by regulating XIAP (X-linked inhibitor of apoptosis protein)." (PMID 33123467, 2020). "Acute lymphoblastic-leukemia (ALL) cells showed comparable triptolide mediated XIAP suppression (10–100 nM, 24–48 h), which was correlated with a reduction in release of cytochrome c mediated by caspase-9 and Mcl1 via the mitochondrial apoptotic mechanism." (PMID 38293343, 2024). "The importance of the Smac/XIAP ratio in treatment responses to Smac mimetics was highlighted in childhood acute lymphoblastic leukaemia where XIAP is upregulated." (PMID 26071313, 2015). "In childhood acute lymphoblastic leukemia (ALL) the XIAP expression is highly increased by post-transcriptional regulation and is associated with poor in vivo glucocorticoid response and outcome." (PMID 25120954, 2014). "In contrast, although originally XIAP deficient mice were reported to have no obvious phenotype, a later publication found that XIAPΔRING mutant mice develop lymphomas and lymphoblastic leukemia." (PMID 32182843, 2020). "XIAP downregulation and Smac mimetics were found to sensitize acute lymphoblastic leukemia (ALL) cells towards chemotherapy and reduce tumor outgrowth in vivo." (PMID 38731935, 2024). "In their recently reported study, Gu and colleagues showed interesting activity of new MDM2 inhibitors that compromise XIAP mRNA translation by targeting the MDM2 RING domain, in an acute lymphoblastic leukaemia model." (PMID 29017180, 2017). "In addition to XIAP over-expression, insufficient expression of TRAIL receptors also contributes TRAIL resistance in many cancers, including in acute lymphoblastic leukemia cells (ALL)." (PMID 28424988, 2017). "Also in childhood T-cell acute lymphoblastic leukemia (ALL), elevated expression levels of XIAP protein turned out to be an unfavorable prognostic factor, as there was a correlation between high XIAP protein expression and poor prednisone response in T-cell ALL." (PMID 24478984, 2014).
Cerebral ischemia (10 papers, 2012 to 2024). Restriction of arterial blood supply to the brain associated with insufficient oxygenation to support the metabolic requirements of the tissue. "In a study of sex-biased vulnerability to cerebral ischemia, it was found that miR-23a targets an X-linked inhibitor of apoptosis (XIAP)." (PMID 38473893, 2024). "Collectively, the results of this study highlights that BMSCs modified by XIAP can inhibit the apoptosis of brain nerve cells and the activation of astrocytes and increase the activity of AchE, so as to lower the CP caused by cerebral ischemia and hypoxia in rats." (PMID 31660045, 2019). "Our study demonstrates that XIAP overexpressed BMSCs can inhibit the apoptosis of brain nerve cells and the activation of astrocytes, increase AchE activity, and inhibit Ach content, so as to lower the CP caused by cerebral ischemia and hypoxia in rats." (PMID 31660045, 2019). "In addition to its role in cardiac function, miR-23a levels also differ in males and females after cerebral ischemia and are related to accelerating apoptosis by regulating X-linked inhibitor of apoptosis (XIAP) expression and XIAP-caspase complex formation." (PMID 29415433, 2018). "XIAP was shown to contribute to the sex difference following cerebral ischemia, where it was reduced significantly in females post-ischemia." (PMID 38473893, 2024). "Increases in tissue preservation agree with the observations by Wang and colleagues in the analysis of the effects of XIAP overexpression after cerebral ischemia using the same strain of transgenic mice." (PMID 36769152, 2023). "Based on this, we have evaluated a pharmacological therapy based on ucf-101, a synthetic heterocyclic compound with neuroprotective effects in animal models of brain ischemia that prevents XIAP cleavage and inhibition through the inhibition of Omi/HtrA2." (PMID 36769152, 2023). "Here, our data confirmed that cerebral ischemia-reperfusion induced XIAP nitrosylation, procaspase-9 denitrosylation and cleavage." (PMID 27052476, 2016). "The potential interplay between caspase 3 and 9 via transnitrosylating to XIAP, leading to apoptosis, particularly in a cerebral ischemia-reperfusion event is underway in our lab." (PMID 27052476, 2016). "So we presume that procaspase-9 transnitrosylates the RING finger domain of XIAP to inhibit its E3 ligase activity and promote apoptosis during cerebral ischemia-reperfusion or OGD/reoxygenation." (PMID 27052476, 2016). "The reverse trend of the time course of the S-nitrosylation of procaspase-9 and XIAP suggests the possibility that procaspase-9 transnitrosylates XIAP during cerebral ischemia-reperfusion." (PMID 27052476, 2016). "In this study, we for the first time reveal that SNO-procaspase-9 transnitrosylates XIAP, contributing to its cleavage during cerebral ischemia-reperfusion, and that the transnitrosylation occurs between procaspase-9 and XIAP." (PMID 27052476, 2016). "Our data confirmed that cerebral ischemia-reperfusion induced XIAP nitrosylation, procaspase-9 denitrosylation and cleavage." (PMID 27052476, 2016). "For example, sex differences in miR-23a expression and its effect on one of its mRNA targets, X-linked inhibitor of apoptosis (XIAP), are responsible for the sex-specific activation of cell death in a model of cerebral ischemia." (PMID 23009289, 2012). "Accordingly, we examined whether procaspase-9 could transnitrosylate XIAP and enhance its cleavage and the consequent neuronal apoptosis during cerebral ischemia." (PMID 27052476, 2016). "In this study, we demonstrated that cerebral ischemia-reperfusion enhanced the interaction between procaspase-9 and XIAP, and pretreatment with TAT-AVPY [which can competitively bind the third baculoviral IAP repeat (BIR3) domain of XIAP] significantly inhibited this interaction." (PMID 27052476, 2016).
Cerebral ischemia (continued). "Interestingly, the time courses of the nitrosylation of procaspase-9 and XIAP were negatively correlated, which was more prominent after cerebral ischemia-reperfusion, suggesting a direct interaction." (PMID 27052476, 2016). "Considering this, we used imunoprecipitation to test whether XIAP interacts with procaspase-9 during cerebral ischemia-reperfusion." (PMID 27052476, 2016). "Hence, we confirm that the Trx1 system mediates the process by which procaspase-9 transnitrosylates XIAP during cerebral ischemia-reperfusion." (PMID 27052476, 2016). "During cerebral ischemia, mature Smac/DIABLO interacts with XIAP in the cytosol, which abrogates the anticaspase function of XIAP and triggers caspase-3 dependent apoptosis." (PMID 26187498, 2015). "The overexpression of XIAP could protect CA1 hippocampal neurons and retinal ganglion cells from apoptosis in rat brain ischemia model and optic nerve axotomy model." (PMID 37055866, 2023).
esophageal cancer (10 papers, 2013 to 2023). A primary or metastatic malignant neoplasm involving the esophagus. "Low NDRG2 expression is associated with pAKT and XIAP upregulation, while overexpression of NDRG2 suppresses AKT/XIAP signaling pathway and EMT in esophageal cancer cells." (PMID 36012631, 2022). "XIAP may promote migration of esophageal cancer cells through the activation of TGF-β mediated EMT." (PMID 31548877, 2019). "Treatment of XIAP siRNA in combination with paclitaxel, cisplatin, fluorouracil, and etoposide enhanced chemosensitivity in esophageal carcinoma cell lines demonstrating that knockdown of XIAP may be a strategy for cancer therapy in patients with esophageal carcinoma." (PMID 25120954, 2014).
Splenomegaly (10 papers, 2015 to 2023). Abnormal increased size of the spleen. "The incidence of HLH in XIAP deficiency is approximately 60%, whilst half have splenomegaly and a quarter develop Crohn’s disease-like colitis." (PMID 38022498, 2023). "Taken together, our data reveal a novel mutation in a patient suffering from recurrent HLH, IBD and splenomegaly, typical conditions associated with XIAP deficiency." (PMID 32514016, 2020). "The XIAP mutation described here can thus explain both recurrent episodes of fever with mild splenomegaly, which likely represent incomplete bouts of lymphohistiocytosis, and intractable inflammatory colitis." (PMID 26671016, 2015). "Indeed, expression of a kinase-activating C-RAF mutant, C-RAF(L613V), in a murine model of Noonan syndrome, results in splenomegaly, a phenotype also associated with XIAP-deficient patients." (PMID 35562367, 2022). "Immunisation of mice with alum, an agent that induces an inflammatory response primarily driven by NLRP3 inflammasome activation, caused splenomegaly and elevated splenic infiltration of inflammatory cells, which is reminiscent of the splenomegaly observed in XIAP deficient patients." (PMID 34222142, 2021). "Interestingly, XIAP-deficient mice challenged with MHV-68 as a surrogate for EBV infection, or C. albicans developed splenomegaly with increased levels of proinflammatory cytokines." (PMID 36329240, 2023). "XIAP deficient patients were initially observed to suffer from similar symptoms to SAP deficient patients, including HLH that was frequently triggered by an EBV infection, splenomegaly, cytopaenias, and hypogammaglobulinemia." (PMID 34222142, 2021). "However, XIAP-deficient patients also present with hemophagocytic lymphohistiocytosis (HLH), recurrent fevers, recurrent low blood counts and splenomegaly, which may be due to XIAP’s role in regulating caspases or alternative signalling pathways." (PMID 35562367, 2022). "Surprisingly, patients with Cryopyrin-associated periodic syndrome (CAPS), which is caused by a gain-of-function mutations in the NLRP3 gene, do develop recurrent fever, uveitis and arthritis, similar to XIAP deficient patients, but do not develop HLH, splenomegaly or IBD." (PMID 34222142, 2021).
Crohn disease (9 papers, 2015 to 2026). A gastrointestinal disorder characterized by chronic inflammation involving all layers of the intestinal wall, noncaseating granulomas affecting the intestinal wall and regional lymph nodes, and transmural fibrosis. "In conclusion, our study identifies tuft cell deficiency as a trigger of intestinal pathology in XIAP‐-deficient Crohn's disease and suggests JAK inhibition as a promising therapeutic strategy." (PMID 42039706, 2026). "Loss of NF-κB signalling results in a failure to up-regulate cytokines in response to NOD2 signalling and this link to NOD2 signalling is thought to be the cause of Crohn’s disease in XIAP deficient patients." (PMID 29743550, 2018). "Indeed, a frequent occurrence of private variants of the X-linked inhibitor of apoptosis protein has been associated with Crohn’s disease." (PMID 32582690, 2020). "IAP inhibition or loss of both cIAP2 and XIAP resulted in a strong blockage in autophagic flux and mitophagy, suggesting that XIAP deficiency may also drive Crohn’s Disease due to defects in autophagy." (PMID 29743550, 2018). "Crohn’s disease is also caused by mutations in the gene encoding NOD2 but the mechanisms behind Crohn’s disease development in XIAP and NOD2 deficient-patients are still unknown." (PMID 29743550, 2018). "This suggests that the driving mechanism behind multiple genetic mutations causing Crohn’s Disease may be a loss of autophagy, and supports a role for XIAP in regulating this process." (PMID 29743550, 2018). "Loss of XIAP in humans causes X-linked Lymphoproliferative disease type 2 (XLP-2) and is often associated with Crohn’s disease." (PMID 29743550, 2018). "Together these data suggest that autophagy is a key pathway linking NOD2 and ATG16L1 in the development of Crohn’s disease and hint that XIAP may also have some role in autophagy regulation." (PMID 29743550, 2018).